NR4A1AS (NR4A1 antisense RNA)
Synonyms: NR4A1-AS1; RP11-1100L3.8; lncMMPA
Gene: Long non-coding RNA gene on chromosome 12 (52,058,459 to 52,059,503, reverse strand). Ensembl gene ENSG00000259884.
Diseases named in the same sentence as NR4A1AS in open-access papers:
NR4A1AS is named in the same sentence as 3 diseases in open-access papers, as found by Europe PMC text mining. Sharing a sentence is not in itself a finding about the gene and the disease. The quoted sentences say what the papers report.
colorectal cancer (1 paper, 2024). A primary or metastatic malignant neoplasm that affects the colon or rectum. "Interestingly, the expression of an antisense lncRNA against NR4A1, NR4A1AS, was shown to modulate NR4A1 expression in colorectal cancer cells." (PMID 38791553, 2024).
oral squamous cell carcinoma (1 paper, 2022). "NR4A1AS was upregulated in oral squamous cell carcinoma and promoted the proliferation of oral squamous cell carcinoma cells by upregulating miR-221 through demethylation." (PMID 36268283, 2022).
tumor (1 paper, 2021). "LINC00702, AC121247.2, HSD11B1-AS1, NR4A1AS, AC011472.4, LIPE-AS1, etc., were lower expressed in tumor tissues, conversely, AP001434.1, LINC02257, LINC01655, LINC01614, AF015262.1, LMNTD2-AS1, etc., were highly expressed in tumor tissues." (PMID 34671639, 2021).